HEYL (hes related family bHLH transcription factor with YRPW motif like)
Diseases named in the same sentence as HEYL in open-access papers (continued):
Sharing a sentence is not in itself a finding about the gene and the disease.
COVID-19 (1 paper, 2022). A disease caused by infection with severe acute respiratory syndrome coronavirus 2. "We found that partial-methylated of HeyL promoter increased the risk of COVID-19 in aging patients older than 50 years old 10.2 times than patients who were less than 50 years old." (PMID 35655915, 2022). "Also, we found that partial-methylated of HeyL promoter was associated with severe illness in COVID-19 patients." (PMID 35655915, 2022). "We identified unmethylated CpG (TG) flanking the response elements within HeyL promoter in Egyptian COVID-19 patients and control healthy subjects vs. methylated CpG (CG) in reference sequence (GenBank)." (PMID 35655915, 2022). "We found that the HeyL promoter was partial-methylated in Egyptian COVID-19 patients and control healthy subjects compared to full methylated one that was published in GenBank." (PMID 35655915, 2022). "We observed that the methylation status of HeyL promoter in Egyptian COVID-19 and control healthy subjects was lower than that in the published reference sequence." (PMID 35655915, 2022). "Of note, partial-methylated HeyL promoter was more frequent in aging COVID-19 patients who were equal or more than 50 years old compared to those who were less than 50 years old (P = 0.0158)." (PMID 35655915, 2022). "Administration of therapy must be based on determination of methylation status of HeyL, a novel prognostic marker for severe illness in COVID-19 patients." (PMID 35655915, 2022). "To investigate the effect of methylation status on the HeyL promoter action, we compared the binding sites in both COVID-19 patients and control with those in reference sequence using Ensembl program." (PMID 35655915, 2022). "In electrophoretic separation, the amplicon products of MSP showed that partial-methylated HeyL promoter (methylated+unmethylated bands) among COVID-19 patients was more frequent compared to control subjects who showed more unmethylated bands." (PMID 35655915, 2022). "Our data revealed that methylated HeyL promoter may be a prognostic marker for severe illness in COVID-19 patients." (PMID 35655915, 2022). "In addition, we identified unmethylated and partial-methylated KLF binding sites among HeyL promoter in COVID-19 patients vs. the consensus sequence of KLF (CACCC)." (PMID 35655915, 2022). "The observed poor prognosis in COVID-19 patients who showed severe illness may be attributed to the improper binding of regulatory TFs to their response elements in HeyL promoter, subsequently, interfering with the regulatory role of HeyL." (PMID 35655915, 2022). "Also, we found that the mCpG rates were ranged from 11.15% to 75.0% in COVID-19 patients vs. 14%-75% in control healthy subjects compared to full methylated HeyL promoter in reference sequence." (PMID 35655915, 2022). "Also, we found that binding sites in Egyptian HeyL promoter were hypomethylated than those in reference sequence; however, the methylation status of binding sites in COVID-19 patients was higher than control healthy subjects." (PMID 35655915, 2022). "Our objective was achieved by DNA sequencing of the product from methyl-specific PCR of HeyL promoter after bisulfite modification of DNA extracted from the blood samples of 30 COVID-19 patients and 20 control health subjects and studying its association with clinical-pathological biomarkers." (PMID 35655915, 2022). "Subsequently, our finding may emerge a novel role of HeyL in atherogenesis related to COVID-19 patients via mediating the action of KLF signal." (PMID 35655915, 2022). "Thus, we aimed to monitor its methylation status and its impact on the response elements within HeyL promoter in COVID-19 patients and, in addition to, study its correlation with the clinical outcomes and the routine biomarkers including PLR, CRP, ferritin and D-dimer." (PMID 35655915, 2022).
COVID-19 (continued). "Also, our data indicated that the relevance of detecting the methylation status of HeyL promoter did not have only a prognostic value, but also being as a target for novel antiviral therapies which may add benefits in counteracting the severe illness in COVID-19 patients." (PMID 35655915, 2022).
embryonal rhabdomyosarcoma (1 paper, 2020). A poorly circumscribed morphologic variant of rhabdomyosarcoma. "Although embryonal rhabdomyosarcoma most likely arises from myoblasts, both markers of quiescent satellite cells, e.g., PAX3, PAX7, or HEYL, and markers of activated satellite cells, including MYOD1, are frequently expressed." (PMID 31941033, 2020).
endometrial cancer (1 paper, 2013). Primary or metastatic malignant neoplasm involving the endometrium (mucous membrane that lines the endometrial cavity). "All these results indicate that HAND2 and the interaction neighbourhood of HAND2, including GATA4, HEYL, and PHOX2A, represent a core component that is epigenetically deregulated in endometrial cancer." (PMID 24265601, 2013).
hemangioma (1 paper, 2011). A benign vascular lesion characterized by the formation of capillary-sized or cavernous vascular channels. "Protein expression evaluation by immunofluorescence confirms that HEY2 is expressed by HemECs (CD31+ cells), while HEY1, HEYL, and HES1 are more widely expressed and mostly expressed by perivascular cells of hemangiomas." (PMID 21834989, 2011).
infantile hemangiomas (1 paper, 2011). "After analysis of eight members of the HES/HEY family, we found that HES1, HEY1, HEY2 and HEYL are expressed in infantile hemangiomas." (PMID 21834989, 2011).
liver cancer (1 paper, 2021). An epithelial or non-epithelial malignant neoplasm that arises from the liver. "Human studies have shown that HEYL regulates differentiation of fetal neural stem cells and proliferation of breast, prostate and liver cancer cells." (PMID 34831437, 2021).
metastatic disease (1 paper, 2019). "Our study reveals an association between high expression of the Notch target gene HEYL and metastatic disease in CRC patients." (PMID 31796022, 2019).
Obstructive Lung Disease (1 paper, 2021). "Finally, the lack of information regarding Global Initiative for Obstructive Lung Disease (GOLD) stages of our COPD HBEC donors prevents us from correlating disease severity with differentiation capacity and expression of HEYL." (PMID 34831437, 2021).
prostate adenocarcinoma (1 paper, 2021). "To determine the potential mechanism regulated by HeyL, we individually selected prostate adenocarcinoma samples in the top quartile of the HeyLHigh and HeyLLow groups from TCGA and performed GSEA on these samples." (PMID 35096586, 2021).
small cell lung carcinoma (1 paper, 2010). Small cell lung cancer (SCLC) is a highly aggressive malignant neoplasm, accounting for 10-15% of lung cancer cases, characterized byrapid growth, and early metastasis. "HEYL was found to have increased expression associated with amplification in small cell lung cancer." (PMID 20844748, 2010).
viral infection (1 paper, 2022). "Moreover, our data may suggest that the presence of methylated E-Box in HeyL promoter may interfere with the binding of USF-1, subsequently impairing its regulatory action on the lung-specific glycoprotein, inflammatory process, and the pulmonary epithelium, especially, during viral infection." (PMID 35655915, 2022).
tumor (19 papers, 2013 to 2024). "Our results showed that the expression levels of HEYL and tumor stage III, IV were independent prognostic risk factors which correlated with patients’ dismal survival (P < .05)." (PMID 32463580, 2020). "Mechanistically, we demonstrated that Notch3 prevents tumor initiation via HeyL-mediated inhibition of Mybl2, an important regulator of cell cycle." (PMID 36854682, 2023). "Higher expression of CXCL13 and HEYL in tumor cell than normal cell was found, as well as the lower expression of ANKRD35 and PDCD1LG2." (PMID 37397391, 2023). "IHC analysis was carried out to evaluate the protein expression of HeyL in benign prostate (n=9), primary PCa (n=23), and CRPC (n=15) samples." (PMID 35096586, 2021). "We have shown that HEYL increased the expression of several angiogenic cytokines and enhanced angiogenesis and tumor growth by its action in both epithelial and endothelial cells." (PMID 33520697, 2020). "Carcinomas arising in double transgenic Her2-neu/HeyL mice showed higher tumor vessel density and significantly faster growth than tumors in parental Her2/neu mice." (PMID 33520697, 2020). "Supporting these findings, suppressing HEYL expression using shRNA in MDA-MB-231 cells significantly reduced tumor growth." (PMID 33520697, 2020). "Here, we show that HEYL expressed in tumor epithelial cells increased expression of multiple angiogenic factors and promoted neoangiogenesis, while HEYL expression in endothelial cells appears to promote invasive growth behavior of endothelial cells." (PMID 33520697, 2020). "Adequately, we further validated the expression levels of HEYL in our internal 117 GC paired tissues, the HEYL was significantly upregulated in tumor samples compared with normal gastric tissues at the mRNA levels (P < .001)." (PMID 32463580, 2020). "Multivariate results implied that the expression level of HEYL, tumor stage, and tumor size represented the approximate power to estimating GC patients’ prognosis (P < .05)." (PMID 32463580, 2020). "Our functional assays indicate an important role for epithelial HEYL expression in the promotion of tumor angiogenesis." (PMID 33520697, 2020). "HEYL overexpression decreased tumor cell dissemination and the absolute numbers of formed metastases in a sub-renal capsular spontaneous metastasis formation model, addressing all steps of the metastatic cascade." (PMID 31796022, 2019). "Supporting the case for Notch as a tumor suppressor, Belandia and colleagues reported that Hey1 and HeyL are excluded from the nucleus upon the transition from benign to carcinoma in human prostate samples." (PMID 24199173, 2013). "Therefore, the 5-AZA-CdR treatment-dependent enhancement of HEYL regulon activity is beneficial for the anti-tumor effects." (PMID 36882403, 2023). "Thus, HEYL expression in tumor epithelium has a profound effect on the vascular microenvironment in promoting neoangiogenesis." (PMID 33520697, 2020). "In addition, we found that HEYL expression in both tumor epithelial and endothelial cells has functional consequences." (PMID 33520697, 2020). "We hypothesized that HEYL expression in the tumor cells, in all likelihood, promotes angiogenesis through upregulation and expression of these and other chemokines." (PMID 33520697, 2020). "Notably, knockdown of HEYL level observably decrease tumorigenicity in nude mice, as determined by tumor weight and tumor size." (PMID 32463580, 2020). "In summary, we found that HEYL is expressed in both tumor epithelial and endothelial cells." (PMID 33520697, 2020). "HEYL may have angiogenic effects through overexpression in two different tumor cellular compartments." (PMID 33520697, 2020). "Direct evidence was sought for HeyL’s involvement in mouse tumor angiogenesis and growth in vivo." (PMID 33520697, 2020).
tumor (continued). "The notch pathway has been shown to be involved in the metastatic spread of various tumor entities, whereas the impact of its target gene HEYL in the context of metastasis so far remains unclear." (PMID 31796022, 2019). "The notch pathway has been shown to be involved in the metastatic spread of various tumor entities; however, the impact of its target gene HEYL remains unclear so far." (PMID 31796022, 2019). "For example, if Myc is the primary target, the pathway may be oncogenic; however, if HeyL is the primary target, it may be tumor suppressive." (PMID 24199173, 2013). "Since these mice lack HEYL expression in all cell types, we do not know whether the impeded tumor growth is due of HeyL loss in endothelial cells or in any other cell population." (PMID 33520697, 2020). "The fact that HEYL overexpression induced significant reduction in the number of metastases in M1 and loss of detectable tumor cell dissemination into the bone marrow in NM1 cell-transplanted mice, indicates that HEYL may act as a negative regulator of metastatic capacity in CRC." (PMID 31796022, 2019). "HEYL, SLC2A3, and FBN1 were found to mediate tumor progression and chemoresistance mainly by facilitating angiogenesis and EMT, while CERCAM, ANXA1, and SPOCD1 promoted tumor progression through the PI3K/AKT and EGFR signaling pathways." (PMID 39033778, 2024). "The activation of STAT1-related antiviral immunity and the restoration of tumor suppressive TF activities of HEYL and PITX1 would synergistically contribute to the anti-tumor effects of 5-AZA-CdR treatment." (PMID 36882403, 2023). "In bioproven GC individuals, the HEYL mRNA and serum CA19‐9 levels (kU/L) were used to construct a ROC curve to fully calculate the predicting accuracy for GC stage, OS, and tumor recurrence estimation." (PMID 32463580, 2020). "Genes such as CFLAR, EP300, GBP2, HEYL, KLF7, NOTCH1 or POFUT showed a similar correlation with NUMB or NUMBL in the three tumor types considered." (PMID 29507685, 2018). "We found a dramatic upregulation of the canonical NOTCH1 target gene HEYL and a concurrent downregulation of HMGA1 and HMGA2 in fibroblasts co-cultured with JAG1-expressing tumour cells, particularly A549 and Hep3B cells." (PMID 29743479, 2018). "When TCGA patients with lung SCC were categorised based on expression into ‘HMGA1 high–HEYL low’ and ‘HMGA1 low–HEYL high’ tumours, patients in the former category had a better overall survival (p = 0.00316)." (PMID 29743479, 2018). "Absence of HEYL in the HEYL-/- mice impaired physiological retina blood vessel development and tumor growth of syngeneic cancer cells." (PMID 33520697, 2020). "There was a significant negative correlation between HMGA1 and HEYL in the majority of tumour types analysed and a particularly strong anti-correlation in lung SCC (R = −0.4842; p = < 0.0001)." (PMID 29743479, 2018). "Thus, thanks to the high sensitivity of Well-TEMP-seq, we can provide insights into the 5-AZA-CdR induced anti-tumor response of STAT1, HEYL, and PITX1 TFs activation in the early stage of treatment (e.g., in the first three days), which has not been unveiled before." (PMID 36882403, 2023). "Similarly, slower growth of syngeneic E0771 tumor cells in HEYL-/- mice may occur due to lack of HEYL in other cell types in the tumor microenvironment or due to distant effects." (PMID 33520697, 2020). "In summary, our data indicate that HEYL overexpression in patient-derived CRC cells impairs their metastasis formation capacity as detected by a decreased number of distant metastases or lack of mice with disseminated tumor cells into the bone marrow following sub-renal capsular xenotransplantation." (PMID 31796022, 2019).
cancer (17 papers, 2013 to 2026). A tumor composed of atypical neoplastic, often pleomorphic cells that invade other tissues. "Our findings indicate that tumors with elevated expression levels of HEYL, RPS17, and JDP2 are associated with a poorer prognosis for cancer patients." (PMID 39676867, 2024). "Other transcription factors are associated with cancer-related pathways, such as NPAT, ZNF264, HEYL and ETV4." (PMID 33525507, 2021). "The expression of HeyL, together with the stemness-associated genes SOX2, OCT4, KLF4, and CD44, was significantly increased in PCSCs compared with the corresponding bulk cancer cells." (PMID 35096586, 2021). "Since Notch signaling is involved in the metastatic spread of various tumors, HEYL is also supposed to participate in the progression and metastasis of cancer." (PMID 34349799, 2021). "Meanwhile, HEYL enhances carcinogenesis and metastasis through activating cancer‐related signaling pathways by regulating CDH11 expression level in GC cells." (PMID 32463580, 2020). "Furthermore, we show that lack of HEYL expression in endothelial cells leads to defects in neoangiogenesis, both under normal physiological conditions and in cancer." (PMID 33520697, 2020). "One study regarding the integrative genomic analyses of the HES/HEY family presumed that Notch-independent HES1 and 3 transcription occurred in undifferentiated ES cells, and that Notch-dependent HES1 and 5, HEY1 and 2, and HEYL transcription occurred in fetal, adult or cancer tissue." (PMID 23420695, 2013). "A collation of 73 TEC marker genes from five studies showed that at most, only two cancer types shared one of these five genes (EGFL6, HEYL, MMP9, SPARC, PLXDC1), and the rest were expressed uniquely in only one cancer." (PMID 32375250, 2020). "We also found a significant negative correlation between HMGA1 and HEY1 in various cancer types, which were not completely overlapping with those where HMGA1 and HEYL anti-correlate." (PMID 29743479, 2018).
HEYL also shares sentences with these, for which no sentence is quoted: breast neoplasm (2 papers); bladder tumor (1); cardiomyopathy (1); congenital myasthenic syndrome (1); coronary artery disease (1); digestive system carcinoma (1); gastric tumors (1); glomerular disease (1); glomerulosclerosis (1); hepatocellular carcinoma (1); lung adenocarcinoma (1); lung squamous cell carcinoma (1); melanoma (1); memory impairment (1); metastasis (1); metastatic cancer (1); myasthenia gravis (1); oral cancer (1); pneumonia (1); type 2 diabetes (1).